BDNF (brain derived neurotrophic factor)
Diseases named in the same sentence as BDNF in open-access papers (continued):
Sharing a sentence is not in itself a finding about the gene and the disease.
psychiatric disorder (continued). "Several candidate genes (e.g: BDNF; FKBP5; SLC6A4; AVP; NR3C1; CRH; COMT; MAOA; OXTR and APOE) to psychiatric disorders have been quoted in epigenetic studies using locus-specific assays." (PMID 30218003, 2018). "In any case, the efficiency of treatments enhancing or mimicking BDNF actions, or those directed to TrkB transactivation, could be dramatically limited if the receptor stability and function were aberrant, as is frequently the case in neurological and psychiatric disorders." (PMID 28134845, 2017). "Brain-derived neurotrophic factor (BDNF) is abundant in the hippocampus and plays critical roles in memory and synapse formation, as well as exerting antidepressant-like effects in psychiatric disorders." (PMID 28872625, 2017). "Enhancement of brain-derived neurotrophic factor (BDNF) signalling has great potential in therapy for neurological and psychiatric disorders." (PMID 28134845, 2017). "Therefore, much attention has been given to BDNF because specific interference with BDNF-related signaling is regarded as a leading strategy to stimulate neuronal and synaptic plasticity for potential protective and functionally restorative treatments for neurological and psychiatric disorders." (PMID 28280960, 2017). "In particular, recent studies in humans and mutant mouse models suggest biological epistasis between BDNF and another gene involved in serotonin regulation (serotonin transporter, SLC6A4) that may alter neural circuitry and thereby influence risk for psychiatric disease." (PMID 27695066, 2016). "Plasma concentrations of BDNF, IGF-1 and IGFBP-3 in abstinent cocaine users grouped by diagnosis of common psychiatric disorders in substance users." (PMID 25734326, 2015). "Substantial evidence indicates neurotrophic/growth factors such as BDNF and IGF-1 are involved in the pathogenesis of common psychiatric disorders." (PMID 25734326, 2015). "The BDNF/proBDNF ratio has not been studied as extensively in psychiatric disorders compared to the level of BDNF itself." (PMID 40002454, 2025). "The brain-derived neurotrophic factor (BDNF) involves stress regulation and psychiatric disorders." (PMID 38252222, 2024). "Moreover, studies demonstrated that BDNF and SERT in patients’ peripheral blood indicate a psychiatric disorder." (PMID 37396946, 2023). "In addition, we analyzed changes in TPH2, BDNF, and GDNF in mental illness suicide (PI) and life event suicide (LE)." (PMID 37509026, 2023). "Patients with psychiatric disorders were shown to have increased Gadd45b-stained cells in prefrontal cortex layers II, III, and V. This research demonstrated that individuals with psychiatric disorders bind less Gadd45b to the BDNF promoter." (PMID 36311022, 2022). "At present, despite extensive studies on BDNF methylation and the development of various psychiatric disorders, changes in methylation have not been used as a specific biomarker for certain psychiatric phenotypes." (PMID 35853898, 2022). "GSK3B, BDNF, NGF, NRG1, HTR2C, and PIP4K2A are genes that showed some importance in the study of the molecular etiology of psychiatric disorders." (PMID 33193575, 2020). "Previous research showed that there was a negative correlation between mature Brain-derived neurotrophic factor in parietal cortex and in liver which indicated that there is a liver-brain axis in psychiatric disorders." (PMID 32489401, 2020). "Abundant genetic studies have shown the possible correlation between BDNF gene polymorphisms and SCZ even though some studies have not found any correlation between BDNF Val66Met polymorphism and psychiatric disorder." (PMID 29472953, 2017). "Non-addictive psychiatric disorders were not ascertained through standardized questionnaires, so that the relationship between BDNF and SA could have been confounded by conditions such as major depression." (PMID 33479229, 2021). "Studies have shown that a lack of BDNF can lead to mental disorders and neurodegenerative diseases." (PMID 35194435, 2021).
psychiatric disorder (continued). "However, combining tPA, PAI-1, BDNF, proBDNF, TrkB and p75NTR could differentiate MDD from HCs and other mental illness." (PMID 28761093, 2017). "BDNF levels could be considered as a marker for the presence of a nonspecific psychiatric disorder and possibly a transdiagnostic and nonspecific marker of disease activity." (PMID 27959329, 2016). "In summary, the present study has demonstrated a lack of association between the two genetic variants (BDNF rs6265 and DRD2 rs1799978) and MMT response, contrary to what previously had been believed about the role of these variants in psychiatric disorders and addictive behavior." (PMID 26437921, 2015). "This suggests that the reductions in BDNF that we found in all three major mental illnesses may have been greater if we had studied only those without a history of AD or MS use." (PMID 24802307, 2014). "Studies using post-mortem brain samples showed a reduction in BDNF protein in the hippocampus and PFC of psychiatric disorder patients who had committed suicide, compared with non-psychiatric controls." (PMID 25628381, 2014).
neurodegenerative disease (535 papers, 2007 to 2026). A disorder of the central nervous system characterized by gradual and progressive loss of neural tissue and neurologic function. "BDNF plays a crucial role in synaptic plasticity, neuronal survival, and cognitive function, and its disruption is commonly associated with neurodegenerative diseases and pesticide-induced neurotoxicity." (PMID 40283093, 2025). "In contrast, insufficient or reduced BDNF leads to synaptic dysfunction or loss, which accelerates neuronal death and apoptosis and has been implicated in the pathology of several neurodegenerative diseases as well as in their physiological symptoms." (PMID 40429646, 2025). "Reduced BDNF protein and/or mRNA levels in the brain have been associated with their involvement in the pathophysiology of AD and other neurodegenerative diseases." (PMID 40231522, 2025). "Diets that up-regulate BDNF are co-related with improved cognitive performance in at risk populations such as senescence and in neurodegenerative diseases." (PMID 40362507, 2025). "The Met allele has been proposed to influence susceptibility to neurodegenerative diseases by affecting BDNF function." (PMID 40003622, 2025). "BDNF also plays a significant role in the development of Aβ plaques, which are closely associated with neurodegenerative diseases such as AD and Parkinson’s disease (PD)." (PMID 39851517, 2025). "This also serves to emphasize that the emergence of mRNA therapeutics is a new paradigm in providing a non-invasive and largely scalable means to promote BDNF expression in brain regions susceptible to neurodegenerative disease." (PMID 40362507, 2025). "Over the long term, consistently higher levels of BDNF are associated with better cognitive function and possibly lower risk of neurodegenerative diseases." (PMID 40757562, 2025). "Decreased expression of BDNF has been associated with impaired neuronal circuitry, playing an important role in the development of neurodegenerative diseases." (PMID 40565209, 2025). "The decreased synthesis and release of BDNF are strongly implicated in the pathophysiology of neurodegenerative diseases such as AD, PD, multiple sclerosis, and amyotrophic lateral sclerosis." (PMID 41562905, 2025). "Taken together, these data underline the importance of BDNF/TrkB signaling for the development and survival of nigrostriatal neurons, as well as for the function of SPNs in health and neurodegenerative diseases." (PMID 39200225, 2024). "The symptoms seen in various neurodegenerative diseases such as AD, PD, and HD have been associated with a decrease in BDNF levels and changes in signaling pathways." (PMID 39770989, 2024). "Multiple neurodegenerative diseases, including Parkinson’s and Alzheimer’s, have been linked to diminished BDNF expression." (PMID 39077458, 2024). "Changes in BDNF levels and signaling pathways have been identified in several neurodegenerative diseases, including AD, PD, and HD, and have been linked with the symptoms and course of these diseases." (PMID 38891863, 2024). "In fact, dysregulation of BDNF signaling pathway is linked to various neurodegenerative diseases, including PD, and serum levels of BDNF in BP sera is even lower than in PD sera." (PMID 39267741, 2024). "Altered BDNF production and secretion has been implicated in a number of neurodegenerative diseases." (PMID 38665935, 2024). "Due to its ability to cross the blood-brain barrier, peripheral BDNF exerts a central effect on neuron growth and survival, improves memory performance and reduces the risk of neurodegenerative diseases." (PMID 39770947, 2024). "According to numerous research, high levels of BDNF are connected to a lower risk of developing a neurodegenerative disease." (PMID 37287291, 2024). "Several studies have shown that a high level of BDNF is associated with a lower risk of developing a neurodegenerative disease." (PMID 38891863, 2024).
neurodegenerative disease (continued). "BDNF has been implicated in neurodegenerative diseases, and its expression is regulated by the canonical Wnt pathway." (PMID 39167347, 2024). "BDNF‐signalling pathways are highly reduced in ageing and predispose to the progression of neurodegenerative diseases as PD." (PMID 38752280, 2024). "This degenerative disease is associated with lower serum BDNF levels, which can be elevated to a basal level through antidepressant therapy, as has been established by recent meta-analyses." (PMID 39224579, 2024). "Studies proved that reduced levels of BDNF are one of the pathogenesis mechanisms underlying neurodegenerative diseases." (PMID 37140732, 2023). "Low levels of BDNF have been linked to several neurodegenerative diseases, including Alzheimer’s disease and Parkinson’s disease." (PMID 37110506, 2023). "Due to its neuroprotective properties, BDNF has been associated with neurodegenerative diseases, including PD." (PMID 37936189, 2023). "Changed levels of BDNF in the circulation and central nervous system (CNS) have been shown to be associated with the pathogenesis of neurodegenerative diseases, including PD." (PMID 37450039, 2023). "All these proteins are linked to neuronal plasticity in the developing and/or adult brain, and BDNF has been implicated in the pathophysiology of several psychiatric and neurodegenerative diseases including ALS55–60." (PMID 37714849, 2023). "Alterations of BDNF/TrkB signaling in the cortical and hippocampal area, in fact, were indicated as a hallmark of numerous neurodegenerative diseases, and a Trk agonist-mediated restoration holds the promise of a disease-modifying treatment." (PMID 37840771, 2023). "Both BDNF and TrkB are widely distributed within the human brain, and dysfunction of BDNF-TrkB signaling is associated with neurodegenerative diseases." (PMID 37686802, 2023). "Improved BDNF-ERK-CREB signaling is likely an indirect effect of lessening chronic neuroinflammation by hMSC-EVs because decreased BDNF concentrations in neurodegenerative diseases have been linked to a chronic neuroinflammatory environment in the brain." (PMID 37284464, 2023). "Another potential marker implicated in neurodegenerative diseases is the brain-derived neurotrophic factor (BDNF)." (PMID 36844403, 2023). "BDNF gene polymorphisms, specifically the G196A and C270T SNPs, are significantly associated with neurodegenerative diseases, including ALS." (PMID 35743271, 2022). "Several studies have shown that a high level of BDNF is associated with a lower risk for developing a neurodegenerative disease." (PMID 35625880, 2022). "BDNF Val66Met polymorphism influences the risk of neurodegenerative disease development, onset, and pathomechanisms." (PMID 35743271, 2022). "This review summarizes the current understanding of the role of BDNF in several neurodegenerative diseases, as well as the underlying molecular mechanism." (PMID 35743271, 2022). "In this review, we discussed the role of BDNF and the underlying molecular mechanism in the pathophysiology of neurodegenerative diseases." (PMID 35743271, 2022). "The most well-known polymorphism in BDNF gene (rs6265) causes valine to methionine substitution (Val66Met) and it influences memory and motor learning in healthy individuals and neurodegenerative diseases." (PMID 35265024, 2022). "Exercise training has long been established to promote neuroplasticity and attenuate the risk and progression of neurodegenerative diseases, which is likely mediated by the brain-derived neurotrophic factor (BDNF)." (PMID 36742042, 2022). "It is necessary to identify the downstream effectors and dissect the underlying regulatory mechanism of BDNF mediated neuroprotective activity in PD and other neurodegenerative diseases." (PMID 34132500, 2021). "This study highlights the potential of BDNF as a therapeutic candidate for the treatment of mitochondrial impairment‐associated neurodegenerative diseases." (PMID 34132500, 2021).
neurodegenerative disease (continued). "Alterations in miRNAs or in BDNF contribute to the pathogenic mechanisms involved in neurodegenerative diseases or neuropsychiatric disorders." (PMID 33096634, 2020). "Although more studies are needed to validate the in vitro findings in the aging brain, this study sheds light on the potential of BDNF for controlling microglial activation and the inflammation-associated neurodegenerative diseases." (PMID 32664974, 2020). "We reviewed various studies that have shown neuroplasticity effects caused by regulation of BDNF and miRNAs in different neurodegenerative diseases." (PMID 33029119, 2020). "The activation as well as dysfunction of the BDNF-TrkB pathway are associated with neurodegenerative diseases." (PMID 31963575, 2020). "The BDNF Val66Met variant was first identified in the late 1990s and in 2002 the first two genetic studies investigating the BDNF Val66Met polymorphism in the pathogenesis of neurodegenerative disease were published." (PMID 33096634, 2020). "It has been shown that neurodegenerative diseases are closely associated with a neuronal dysfunction and a low level of brain-derived neurotrophic factor (BDNF) in brain regions including the hippocampus." (PMID 30898134, 2019). "Among the neurotrophins, the dysregulation of brain-derived neurotrophic factor (BDNF) has been implicated in enhanced vulnerability to neurodegenerative diseases." (PMID 29896439, 2018). "BDNF has been demonstrated to be linked to neurodegenerative diseases due to the neuroprotective effects." (PMID 30524223, 2018). "Alterations of NGF and BDNF in the brain, and the disrupted binding of NGF and BDNF to their kinase receptors, are both linked to neurodegenerative diseases." (PMID 30223579, 2018). "These emerging results continue to substantiate the role of BDNF Val66Met in the susceptibility and progression of neurodegenerative diseases." (PMID 29896439, 2018). "Aberrant BDNF signaling is involved in several neurodegenerative diseases, including LOAD, in which low levels have been associated with worsening disease and higher levels have been shown to be protective." (PMID 28424591, 2017). "The impairment of the cerebral BDNF pathway is largely involved in impaired cognition associated in animal models of psychiatric, neurologic and neurodegenerative diseases." (PMID 29375397, 2017). "Similar approaches using genetically modified astrocytes overexpressing BDNF or Nrf2 have proven beneficial in models of neurodegenerative diseases where astrocytosis is a hallmark of disease progression." (PMID 23826235, 2013). "Clinical and basic evidence supports the idea that abnormalities in brain neuronal regeneration assisted by BDNF are associated with a wide range of disorders such as neurodegenerative diseases and psychiatric or stress-related conditions." (PMID 23865384, 2013). "Brain derived neurotrophic factor (BDNF) has been implicated in memory, learning, and neurodegenerative diseases." (PMID 22880108, 2012). "Taken together, there is ample evidence to suggest that BDNF is linked to a variety of molecular abnormalities underlying neuropsychiatric and neurodegenerative diseases." (PMID 21247257, 2012). "Notably, we evaluate the BDNF/proBDNF ratio not only as a mechanistic switch between survival and cell death, but also as a potential diagnostic and predictive biomarker for neurodegenerative disease progression." (PMID 40430064, 2025). "Also, brain disorders, including psychiatric and neurodegenerative diseases, are often associated with decreased BDNF levels in the brain." (PMID 40136424, 2025). "Additionally, omega-3s enhance the production of brain-derived neurotrophic factor, a protein that supports neuronal growth and differentiation, while also helping to mitigate inflammation in the brain—a factor linked to neurodegenerative diseases." (PMID 40362745, 2025).